DMD (dystrophin)
Diseases named in the same sentence as DMD in open-access papers (continued):
Sharing a sentence is not in itself a finding about the gene and the disease.
Duchenne muscular dystrophy (continued). "Duchenne muscular dystrophy (DMD) is caused by an X-linked mutation that leads to the absence of dystrophin, resulting in life-threatening arrhythmogenesis and associated heart failure." (PMID 26311238, 2015). "Duchenne muscular dystrophy (DMD), is a lethal form of dystrophinopathy characterized by marked deficiency or absence of subsarcolemmal cytoskeletal protein- dystrophin." (PMID 25935398, 2015). "Duchenne muscular dystrophy (DMD) is an X-linked genetic disease caused by mutations in the dystrophin gene that result in dysfunctional or absent dystrophin protein." (PMID 26137572, 2015). "Duchenne muscular dystrophy (DMD) is a X-linked genetic disease in which the absence of dystrophin leads to progressive lethal skeletal muscle degeneration." (PMID 25999854, 2015). "Duchenne muscular dystrophy (DMD) is caused by absence of the integral structural protein, dystrophin, which renders muscle fibres susceptible to injury and degeneration." (PMID 26113184, 2015). "Out-of-frame deletions in the dystrophin gene usually lead to Duchenne muscular dystrophy (DMD)." (PMID 25643053, 2015). "In Duchenne muscular dystrophy (DMD), which is caused by the absence of dystrophin, either clinical or subclinical dilated cardiomyopathy is invariably present." (PMID 23324314, 2013). "Duchenne Muscular Dystrophy (DMD) is caused by mutations in the DMD gene resulting in an absence of dystrophin in neurons and muscle." (PMID 23922741, 2013). "Duchenne muscular dystrophy (DMD) is an X-linked recessive, progressive muscle wasting disease caused by mutations in the DMD gene that lead to absence of a functional dystrophin protein." (PMID 23618411, 2013). "Duchenne Muscular Dystrophy (DMD) is an incurable muscle wasting disease caused by a vast number of deletions that disrupt the reading frame of the DMD gene, so that no functional dystrophin protein is produced." (PMID 22274137, 2012). "Duchenne muscular dystrophy (DMD) is an X-linked, progressive muscle wasting disease caused by a non-functional dystrophin protein." (PMID 22253880, 2012). "In Duchenne muscular dystrophy (DMD), utrophin, an autolog of dystrophin, can to some extent substitute for the missing dystrophin." (PMID 21970816, 2011). "Duchenne muscular dystrophy (DMD) is an X-linked disorder characterized by a complete lack of dystrophin, which renders the myofiber membrane unstable." (PMID 21798096, 2011). "Duchenne muscular dystrophy (DMD) is an X-linked myopathy resulting from the production of a nonfunctional dystrophin protein." (PMID 21824387, 2011). "Mutations in the DMD gene leading to a complete absence of the dystrophin protein product give rise to the fatal X-linked condition Duchenne muscular dystrophy (DMD)." (PMID 20163697, 2010). "Exon skipping oligonucleotides (ESOs) of 2'O-Methyl (2'OMe) and morpholino chemistry have been shown to restore dystrophin expression in muscle fibers from the mdx mouse, and are currently being tested in phase I clinical trials for Duchenne Muscular Dystrophy (DMD)." (PMID 18384691, 2008). "Duchenne Muscular Dystrophy (DMD) is caused by the lack of a gene product, dystrophin, and affects approximately one in 3,500 male births." (PMID 17726536, 2007). "Background/Objectives: Duchenne muscular dystrophy (DMD) is a genetic disease characterized by a lack of dystrophin caused by mutations in the DMD gene, and some minor cases are due to decreased levels of dystrophin, leading to muscle weakness and motor impairment." (PMID 39846639, 2025). "Duchenne muscular dystrophy (DMD) is a rare genetic disease, causing muscle degeneration due to lack of dystrophin with inadequate muscle regeneration culminating in muscle dysfunction." (PMID 40021828, 2025). "Another no example, Eteplirsen, approved for Duchenne muscular dystrophy, employs exon-skipping technology to restore the dystrophin reading frame and produce functional dystrophin protein." (PMID 41211454, 2025).
Duchenne muscular dystrophy (continued). "In Duchenne muscular dystrophy (DMD), lack of the shorter dystrophin isoforms Dp140 and Dp71 is associated with increased central nervous system (CNS) involvement." (PMID 40552660, 2025). "Duchenne Muscular Dystrophy (DMD) is a severe neuromuscular disorder caused by mutations in the Dmd gene, leading to the lack of expression of the Dystrophin protein." (PMID 40329365, 2025). "Duchenne muscular dystrophy (DMD) results from the lack of dystrophin, a crucial protein for maintaining the integrity of muscle cells." (PMID 40006994, 2025). "Duchenne muscular dystrophy (DMD) is the most frequent, progressive disease caused by a genetic defect that leads to the production of a nonfunctional form of dystrophin, thereby causing premature death." (PMID 40971868, 2025). "Absence of the structural protein, dystrophin, results in the neuromuscular disorder Duchenne Muscular Dystrophy (DMD)." (PMID 39792584, 2025). "In this study, we used DIA MS to analyze 154 serum samples with the aim of studying longitudinal differences between Becker muscular dystrophy (BMD) patients and Duchenne muscular dystrophy (DMD) patients and investigating potential biomarkers of dystrophin expression and functional outcome in BMD." (PMID 40483507, 2025). "Duchenne muscular dystrophy (DMD), caused by the absence of dystrophin encoded by the DMD gene, inflicts continuous degradation and regeneration on myofibres, driving inflammation, fibrosis and ultimately, deterioration of muscle mass and functionality." (PMID 38289345, 2024). "Duchenne muscular dystrophy (DMD) is a severe and progressive genetic condition that causes muscular degeneration and weakening due to a lack of dystrophin, a necessary muscle protein." (PMID 39582913, 2024). "Duchenne muscular dystrophy (DMD) is a rare X-linked genetic syndrome, wherein pathogenic variants of the gene dystrophin cause a lack or absence of a normally functioning dystrophin protein in muscle cells." (PMID 38982973, 2024). "Current gene therapy for Duchenne muscular dystrophy (DMD) utilizes adeno-associated virus (AAV) to deliver micro-dystrophin (μDys), which does not provide full protection for striated muscles as it lacks many important functional domains of full-length (FL) dystrophin." (PMID 39034316, 2024). "In patients with Duchenne muscular dystrophy (DMD), the direct effect of the characteristic lack of dystrophin is the loss of muscle sarcolemma membrane stability, which results in DMD pathology." (PMID 39834392, 2024). "These are Duchenne muscular dystrophy (DMD), a muscular dystrophy altering dystrophin expression, Friedrich's ataxia (FA), a rare neuromuscular condition reducing frataxin expression, and Pompe disease, a lysosomal storage disorder driven by acid α‐glucosidase deficiency." (PMID 38095849, 2024). "Duchenne muscular dystrophy (DMD) is a fatal disorder caused by the absence of a fully functional dystrophin protein in myocytes due to a mutated DMD gene, which encodes the dystrophin protein." (PMID 39595988, 2024). "The two main endpoints were dystrophin expression and change in North Star Ambulatory Assessment (NSAA) score, which rates the performance of various motor abilities in ambulant children with Duchenne Muscular Dystrophy." (PMID 39684857, 2024). "For example, in females with Duchenne Muscular Dystrophy (DMD), a severe X-linked disorder, reportedly all show skewed XCI resulting from the inactivation of the normal parental copy and preferential expression of the X chromosome harboring pathogenic variants in the DMD gene." (PMID 38627676, 2024). "Duchenne Muscular Dystrophy (DMD) is a progressive, genetically defective neuromuscular disease caused by a lack of dystrophin protein, making muscle fibers fragile and prone to death." (PMID 37816796, 2023). "Duchenne muscular dystrophy (DMD) is a fatal, progressive, muscle wasting disease caused by mutations on the X chromosome that lead to an absence of functional dystrophin." (PMID 37435312, 2023).
Duchenne muscular dystrophy (continued). "miR-378 was suggested to serve as a potential biomarker for various conditions, including Duchenne muscular dystrophy (DMD), an incurable, genetic disorder caused by the lack of dystrophin–structural protein in muscles." (PMID 37596327, 2023). "Duchenne muscular dystrophy (DMD) is an X-linked, recessively inherited neuromuscular disorder caused by lack of dystrophin, the protein product of the DMD gene." (PMID 37000843, 2023). "Recently, it has been shown that inhibiting TGF-β can reduce fibrosis and improve regeneration in several genetic forms of myopathy, including dystrophin-negative Duchenne muscular dystrophy and Marfan syndrome." (PMID 36980840, 2023). "Duchenne muscular dystrophy (DMD) is the most severe dystrophinopathy, caused by a total absence of dystrophin." (PMID 37362434, 2023). "Duchenne muscular dystrophy (DMD) is a severe form of muscular dystrophy without an effective treatment, caused by mutations in the DMD gene, leading to the absence of dystrophin." (PMID 37705069, 2023). "Among children, the most common muscular dystrophy is Duchenne muscular dystrophy (DMD), which is an X-linked inherited disease caused by the absence of the protein dystrophin, which is encoded by the DMD gene." (PMID 37626825, 2023). "A prominent example is Duchenne muscular dystrophy (DMD), where dystrophin gene mutations lead to absence of the dystrophin protein." (PMID 34969177, 2022). "This lack of dystrophin‐related membrane stability renders skeletal muscle fibres more susceptible to contraction‐induced sarcolemmal micro‐rupturing, which in turn results in dysregulation of ion homeostasis and forms the corner stone of the calcium hypothesis of Duchenne muscular dystrophy." (PMID 35902360, 2022). "Duchenne muscular dystrophy involves an absence of dystrophin, a cytoskeletal protein which supports cell structural integrity and scaffolding for signalling molecules in myocytes." (PMID 35340200, 2022). "Out-of-frame mutations in the DMD gene cause Duchenne muscular dystrophy (DMD), characterized by lack of dystrophin expression and severe phenotype; while in-frame DMD mutations cause Becker muscular dystrophy (BMD), with reduced protein expression and milder phenotype." (PMID 35269765, 2022). "For example, a mouse model of Duchenne muscular dystrophy lacking functional dystrophin (similar to patients) exhibits only a mild skeletal muscle phenotype and lacks a cardiac phenotype." (PMID 35976056, 2022). "Duchenne muscular dystrophy (DMD) is a progressive, neuromuscular disorder caused by mutations in the DMD gene that results in a lack of functional dystrophin protein." (PMID 35396602, 2022). "In Duchenne muscular dystrophy (DMD), the lack of a functional dystrophin protein causes skeletal muscle weakness, dilated cardiomyopathy, respiratory failure, and premature death." (PMID 35512829, 2022). "Duchenne muscular dystrophy (DMD), an X-linked degenerative muscle disorder, is caused by the absence of a functional dystrophin protein." (PMID 34111527, 2021). "Duchenne muscular dystrophy (DMD) is an X chromosome-linked recessive neuromuscular disorder caused by mutations in the DMD gene and the subsequent lack of dystrophin protein." (PMID 34884867, 2021). "The DE50-MD canine model of Duchenne muscular dystrophy (DMD) has a dystrophin gene splice site mutation causing deletion of exon 50, an out-of-frame transcript and absence of dystrophin expression in striated muscles." (PMID 34384671, 2021). "The main distinction between the two dystrophinopathies is that in Becker muscular dystrophy, the dystrophin protein is partially functional, while in Duchenne muscular dystrophy, there is no dystrophin protein at all." (PMID 34066119, 2021). "Duchenne muscular dystrophy (DMD) is the most common form of muscular dystrophy, caused by the absence of functional dystrophin." (PMID 34822388, 2021).
Duchenne muscular dystrophy (continued). "Duchenne muscular dystrophy (DMD) is a severe, progressive, muscle-wasting disease caused by mutations in the X-linked gene DMD (encoding dystrophin) leading to a lack of dystrophin in muscle." (PMID 34796900, 2021). "In all the experiments, mdx mice, which have a mutation that leads muscle cells to produce a small, nonfunctional dystrophin protein, were used as an animal model of Duchenne muscular dystrophy." (PMID 34205021, 2021). "Absence of dystrophin, an essential sarcolemmal protein required for muscle contraction, leads to the devastating muscle-wasting disease Duchenne muscular dystrophy." (PMID 34389686, 2021). "In Duchenne muscular dystrophy (DMD), the disease caused by a lack of dystrophin, a protein essential for myocyte integrity, dysfunctional autophagy was demonstrated to contribute to muscle weakness and wasting." (PMID 35008897, 2021). "Despite the absence of dystrophin, the overall phenotype of this mouse model is less severe with respect to Duchenne muscular dystrophy." (PMID 34305639, 2021). "Duchenne muscular dystrophy (DMD) is a devastating X‐linked disease characterized by progressive muscle weakness and caused by a lack of dystrophin protein in the sarcolemma of muscle fibres." (PMID 31793167, 2020). "This study revealed a spontaneous partial deletion in DMD gene in a Jack Russell Terrier showing a Duchenne-type muscular dystrophy due to non-functional dystrophin." (PMID 33049940, 2020). "Duchenne muscular dystrophy (DMD) (MIM #310200) is a lethal degenerative neuromuscular disease, characterized by progressive muscular weakness, leading to motor delays, loss of ambulation, respiratory impairment, and cardiomyopathy, due to the loss of the protein dystrophin." (PMID 33029525, 2020). "Duchenne muscular dystrophy (DMD) is a progressive muscle disease, characterized by mutations in the X-linked dystrophin, that has several therapeutic options but no curative treatment." (PMID 32341395, 2020). "The most frequent and one of the most severe forms of all MD is the Duchenne muscular dystrophy (DMD), a muscle pathology caused by the lack of the protein dystrophin." (PMID 32751747, 2020). "PB can be applied to basic research towards the establishment of a therapy model targeting Duchenne muscular dystrophy (DMD), which is a lethal muscle-wasting disease that currently does not have a cure and is caused by a mutated dystrophin gene." (PMID 32204422, 2020). "Duchenne muscular dystrophy (DMD), an X-linked disorder due to lack of dystrophin, is characterized by progressive muscle weakness and myocardial dysfunction." (PMID 33266491, 2020). "In Duchenne muscular dystrophy, a lack of dystrophin leads to extensive muscle weakness and atrophy that is linked to cellular metabolic dysfunction and oxidative stress." (PMID 33002037, 2020). "Duchenne muscular dystrophy is a lethal muscle disease characterized by the absence of dystrophin, which leads to progressive membrane injury and subsequent changes in intracellular Ca2+ homeostasis and cellular dead." (PMID 32153426, 2020). "Duchenne muscular dystrophy (DMD) is an X chromosome-associated monogenic disease, caused by mutations in a gene encoding dystrophin, leading to the lack of functional protein." (PMID 31412923, 2019). "Duchenne muscular dystrophy (DMD) is caused by a lack of dystrophin protein." (PMID 31017936, 2019). "One of the most common forms of muscular dystrophy is Duchenne muscular dystrophy (DMD), which arises due to mutations in the dystrophin gene that result in the complete absence of this large protein that functions in stabilizing the myocyte membrane." (PMID 31443395, 2019). "Duchenne muscular dystrophy (DMD) is a severe, degenerative muscle disease caused by the absence of dystrophin, a large protein that links the cytoskeleton to the surface membrane in muscle cells." (PMID 30912308, 2019).
Duchenne muscular dystrophy (continued). "Transplantation of Pax7-positive cells into mdx mice, the animal model of Duchenne muscular dystrophy (DMD), led to the appearance of dystrophin, a protein which is not present in DMD muscle, causing myofiber membrane fragility and muscle injuries." (PMID 31412558, 2019). "Duchenne muscular dystrophy (DMD) causes progressive disability in 1 of every 5,000 boys due to the lack of functional dystrophin protein." (PMID 29554127, 2018). "Duchenne muscular dystrophy (DMD) is an X-linked, degenerative muscle disease that affects ~ 1 in 5000 males caused by DMD gene mutations and a resulting lack of the protein dystrophin." (PMID 29843823, 2018). "In Duchenne muscular dystrophy, dystrophin is absent, and sarcolemmal neuronal nitric oxide synthase (nNOS) is lost because it is anchored to dystrophin." (PMID 29976853, 2018). "Mice lacking the sarcolemmal protein dystrophin, designated mdx, have been widely used as a model of Duchenne muscular dystrophy." (PMID 30379896, 2018). "Duchenne muscular dystrophy (DMD) is a severe, X-linked neuromuscular childhood disorder caused by mutations in the DMD gene leading to lack of dystrophin." (PMID 30278058, 2018). "Duchenne muscular dystrophy (DMD) is caused by defects in the DMD gene and results in progressive wasting of skeletal and cardiac muscle due to an absence of functional dystrophin." (PMID 28338606, 2017). "Duchenne Muscular Dystrophy (DMD) is a severe muscle disorder caused by lack of dystrophin." (PMID 29263366, 2017). "Duchenne muscular dystrophy, one of the most common lethal genetic disorders, is caused by mutations in the DMD gene and a lack of dystrophin protein." (PMID 27924830, 2016). "Duchenne muscular dystrophy (DMD) is a lethal, progressive neuromuscular disease due to DMD gene mutations resulting in a complete lack of dystrophin in the skeletal muscle and myocardium." (PMID 26513582, 2015). "Characterised as the most severe and aggressive form of all the muscular dystrophies, Duchenne Muscular Dystrophy (DMD) results from a gene mutation at position 21 on the X chromosome and consequently, absent expression of the cytoskeletal protein dystrophin." (PMID 26703720, 2015). "One is to analyze the acute phase of regeneration induced by cardiotoxin (CTX) administration into skeletal muscle, and the other is to investigate the chronic phase of regeneration in Dystrophin gene-deleted (DMD-null) mice, useful model for Duchenne Muscular Dystrophy (DMD)." (PMID 26098312, 2015). "For example, membrane permeability can be altered by aberrant protein-membrane interactions, presence of aggregative proteins or lack of integral membrane proteins, i.e. as seen with dystrophin in patients with Duchenne muscular dystrophy (DMD)." (PMID 25799359, 2015). "Duchenne Muscular Dystrophy is characterized by: near absence of dystrophin in skeletal muscles; low percentage of revertant myofibers; up-regulation of utrophin synthesis; and a high degree of muscle fibrosis." (PMID 26015394, 2015). "Stem cell therapy is a potential promising approach for the treatment of muscular dystrophies such as Duchenne muscular dystrophy, in which muscle fiber degenerates due to lack of the protein dystrophin." (PMID 25945496, 2015). "Duchenne muscular dystrophy (DMD) is a lethal, X-linked muscle-wasting disease caused by lack of the cytoskeletal protein dystrophin." (PMID 25935002, 2015). "The most common and severe form of muscular dystrophy is Duchenne muscular dystrophy (DMD), a disorder caused by the absence of dystrophin, a structural protein found on the cytoplasmic surface of the sarcolemma." (PMID 24947322, 2015). "Duchenne Muscular Dystrophy (DMD) is a genetic disorder which is a result of mutations in the DMD gene, and leading to the absence of the cytoskeletal protein dystrophin." (PMID 26262993, 2015).